PPM1D (protein phosphatase, Mg2+/Mn2+ dependent 1D)
Diseases named in the same sentence as PPM1D in open-access papers (continued):
Sharing a sentence is not in itself a finding about the gene and the disease.
thymic lymphomas (3 papers, 2013 to 2021). "The majority of sequenced thymic lymphomas detected in PPM1D-transgenic mice contained deletions in the tumor-suppressor gene Pten." (PMID 34771656, 2021). "In summary, our data suggest that truncation of Ppm1d might slightly increase frequency of the thymic lymphoma development (1/12 compared to 0/12 tumors in the wild-type animals) although considerably larger animal groups would be required to evaluate the statistical significance." (PMID 32927737, 2020).
brain tumor (2 papers, 2019 to 2025). "Truncated Ppm1d led to reduced brain tumor-free survival in mice (2-fold increase in tumor-associated mortality at 10 weeks, p<0.05)." (PMID 41394550, 2025).
developmental delay (2 papers, 2020 to 2022).
endometrial cancer (2 papers, 2022). Primary or metastatic malignant neoplasm involving the endometrium (mucous membrane that lines the endometrial cavity). "Across adult cancers, we observed PPM1D mutations to be recurrent in 3% of endometrial cancers." (PMID 35105861, 2022).
glioblastoma (2 papers, 2017 to 2021). The most malignant astrocytic tumor (WHO grade IV).
high-grade gliomas (2 papers, 2014 to 2023). "Recent genomic studies of pediatric high-grade gliomas and DIPGs have revealed mutations in histone variant genes encoding histone proteins, Activin A receptor, type I (ACVR1) and protein phosphatase 1D (PPM1D) bringing new insights into the pathogenesis of these malignancies." (PMID 25200322, 2014).
lung squamous cell carcinoma (2 papers, 2020 to 2021). "The analysis of TCGA RNA-seq data demonstrated that mRNA expression of PPM1D was significantly lower in BRCA, kidney chromophobe (KICH), lung squamous cell carcinoma (LUSC), COAD, LUAD, THCA, and UCEC comparing with the corresponding normal tissue." (PMID 34470916, 2021).
mantle cell lymphoma (2 papers, 2016 to 2025). Mantle cell lymphoma is a rare form of malignant non-Hodgkin lymphoma affecting B lymphocytes in the lymph nodes in a region called the ``mantle zone''. "We investigated the pathophysiological significance of PPM1D and its therapeutic targeting by the novel PPM1D inhibitor GSK2830371 in mantle cell lymphoma (MCL)." (PMID 27626308, 2016).
metastatic prostate carcinoma (2 papers, 2013 to 2025). A carcinoma that arises from the prostate gland and has spread to other anatomic sites. "Eight genes (CYC, CYP51A1, DHFR, EBP, KIF15, PPM1D, SQLE, and UMPS) demonstrated strong dependency in cell lines and were also associated with worse prognosis clinically, representing potential therapeutic targets in metastatic prostate cancer." (PMID 40405591, 2025). "The eight genes where higher expression was associated with worse prognosis (CYC, CYP51A1, DHFR, EBP, KIF15, PPM1D, SQLE, and UMPS) represent potential additional therapeutic targets in metastatic prostate cancer." (PMID 40405591, 2025). "In addtion, the identified interactions in metastatic prostate cancer contain several experimentally confirmed targets of hsa-miR-143 and −145, including CLINT1, CDKN1A, IRS1, MAPK7, PPM1D and SOD2." (PMID 23782521, 2013).
Obesity (2 papers, 2019 to 2022). Accumulation of substantial excess body fat. "The expression level of PPM1D protein increases in mice models of obesity, suggesting that PPM1D is involved in lipid metabolism and obesity." (PMID 36233344, 2022). "Ser/Thr protein phosphatase PPM1D is involved in cellular metabolic processes and is a promising target for anti-obesity treatment." (PMID 30811466, 2019). "PPM1D-/--apoE-/- mice showed anti-atherosclerosis and anti-obesity compared with WT mice." (PMID 30811466, 2019).
T-cell lymphoma (2 papers, 2020 to 2021).
thyroid cancer (2 papers, 2021 to 2022). "Therefore, we investigated the cellular response to MDM2 and PPM1D inhibition in two different thyroid carcinoma cell lines, TPC1 and K1." (PMID 36456590, 2022).
triple-negative breast carcinoma (2 papers, 2023 to 2025). An invasive breast carcinoma which is negative for expression of estrogen receptor (ER), progesterone receptor (PR), and human epidermal growth factor receptor 2 (HER2). "In our study, triple-negative breast cancer patients with different senescence subtypes had different drug sensitivities, and small molecule drugs such as the VEGFR inhibitor AMG.706, PPM1D inhibitor CCT007093, and GSK-3α/β inhibitor CHR.99021 were more effective in the TNBCSASP1 subtype." (PMID 37251343, 2023).
-toxicities (1 paper, 2023). "CAR T-induced cytokine release syndrome (CRS) and immune effector cell-associated neuro-toxicities (ICANS) occurred at similar frequencies in patients with and without PPM1D mutations." (PMID 38132396, 2023).
Arrhythmia (1 paper, 2025). Any cardiac rhythm other than the normal sinus rhythm.
brainstem tumors (1 paper, 2022). "Taken together with the histopathological comparisons of these tumors, Ppm1d-mutant IUE brainstem tumors are representative of the tumors observed in human DMG patients." (PMID 35105861, 2022). "We leveraged RNA-sequencing of sgPpm1dexon6 IUE brainstem tumors to identify highly expressed genes and compared this profile with that of PPM1D-mutant human tumors." (PMID 35105861, 2022).
cardiac hypertrophy (1 paper, 2021). "Picrosirius red/Fast Green staining of the heart showed greater levels of fibrosis in the Ppm1d-mutant group, and an increase cardiomyocyte cross-sectional area size that is consistent with greater cardiac hypertrophy." (PMID 34315245, 2021).
cholangiocarcinoma (1 paper, 2021). A carcinoma that arises from the intrahepatic biliary tree (intrahepatic cholangiocarcinoma) or from the junction, or adjacent to the junction, of the right and left hepatic ducts (hilar cholangiocarcinoma). "Interestingly, PPM1D is highly expressed in HCC and CHOL from Sangerbox and TIMER database., and our previous researches have illustrated that PPM1D is associated with poor prognosis of cholangiocarcinoma." (PMID 34470916, 2021).
colon adenocarcinoma (1 paper, 2019).
COVID-19 (1 paper, 2022). A disease caused by infection with severe acute respiratory syndrome coronavirus 2. "In addition, 13 to 16-fold increases in PPM1D expression were found in IgG and IgM plasmablasts, interferon stimulated genes in T4 cells, and developing neutrophils in the COVID-19 samples, while a 12-fold decrease in expression in T.gd cells (γδ T cells) was observed." (PMID 35773312, 2022).
cutaneous squamous cell carcinoma (1 paper, 2024).
heart failure (1 paper, 2021). Inability of the heart to pump blood at an adequate rate to meet tissue metabolic requirements. "We evaluated the causal and mechanistic relationships between Ppm1d-mediated t-CH and nonischemic heart failure in an experimental system." (PMID 34315245, 2021). "Somatic mutations in protein phosphatase Mg2+/Mn2+ dependent 1D (Ppm1d), that frequently occur in cancer survivors with t-CH, contribute to the development of nonischemic heart failure in a murine model." (PMID 34315245, 2021). "Plasma BNP, a heart failure marker, was significantly increased in the Ppm1d-mutant group." (PMID 34315245, 2021). "Thus, the current study was performed to test whether a causal relationship exists between t-CH and nonischemic heart failure by focusing on activating mutations in exon 6 of the Ppm1d gene as a test case." (PMID 34315245, 2021). "By focusing on the DNA-damage response gene Ppm1d, this study indicates that t-CH can contribute to nonischemic heart failure." (PMID 34315245, 2021). "Macrophages harboring mutations in exon 6 of Ppm1d were impaired in DDR pathway activation, displayed an augmented proinflammatory profile, and promoted cardiac dysfunction in a model of nonischemic heart failure." (PMID 34315245, 2021).
lung disease (1 paper, 2023).
myeloproliferative neoplasm (1 paper, 2022). A clonal hematopoietic stem cell disorder, characterized by proliferation in the bone marrow of one or more of the myeloid (i.e., granulocytic, erythroid, megakaryocytic, and mast cell) lineages. "Truncating mutations in the terminal exon of PPM1D have been identified in 1.9% of an MPN cohort, and PPM1D was thus the eighth-most mutated gene in myeloproliferative neoplasms." (PMID 35456443, 2022).
neutropenia (1 paper, 2024). A decrease in the number of neutrophils found in the blood. "The most common side effects include hematologic toxicity, prolonged neutropenia, and infections, while clinical outcomes are highly impacted by many factors, which include a pro-inflammatory state, PPM1D gene mutation, infusion timing, and circulating monocytes." (PMID 39822464, 2024).
polycythemia vera (1 paper, 2022). "The mutated form of PPM1D was subclonal to JAK2V617F in a patient with polycythemia vera." (PMID 35456443, 2022).
renal agenesis (1 paper, 2020). Renal agenesis (RA) is a form of renal tract malformation characterized by the complete absence of development of one or both kidneys (unilateral RA or bilateral RA respectively), accompanied by absent ureter(s). "We detected incidental findings in Case 4 with unilateral renal agenesis (Family 38) and a de novo frame shift variant (c.1434delC) in PPM1D, suggesting a loss‐of‐function mechanism." (PMID 32779812, 2020).
spinal cord astrocytoma (1 paper, 2025). A low or high grade astrocytoma that arises in the spinal cord.
Telangiectasia (1 paper, 2017). Telangiectasias refer to small dilated blood vessels located near the surface of the skin or mucous membranes, measuring between 0.5 and 1 millimeter in diameter. "We also tested whether differences in the way biological entities are named affects recognition and grounding; we found that Wip1, WIP‐1, WIP1, PPM1D, and Protein phosphatase 1D as well as ATM, Atm, and ataxia telangiectasia mutated all worked as expected (bottom, green)." (PMID 29175850, 2017).
teratoma (1 paper, 2024). A non-seminomatous germ cell tumor characterized by the presence of various tissues which correspond to the different germinal layers (endoderm, mesoderm, and ectoderm). "We observed chromothripsis in one tumour (GEL-TGCT-0056), a rare case of metastatic teratoma with somatic-type malignancy, in which a cluster of 23 structural variants arose in a single catastrophic event affecting chromosomes 7 and 17, including amplification of PPM1D." (PMID 39461959, 2024).
Thrombocytopenia (1 paper, 2023). A reduction in the number of circulating thrombocytes. "Our data indicate that inhibition of PPM1D may be well tolerated, and notably, it does not cause thrombocytopenia, a common toxicity associated with other modulators of the DDR, including the nutlin class of drugs." (PMID 37595362, 2023).
thyroid (1 paper, 2019). "In the PPM1D gene two variants were detected in our cohorts with probably benign significance on thyroid tumorigenesis." (PMID 31085772, 2019).
thyroid nodule (1 paper, 2019). A small circumscribed mass in the THYROID GLAND that can be of neoplastic growth or non-neoplastic abnormality. "Some of the identified variants in the CHEK2 gene are pathogenic or likely pathogenic and the influence of found variants in the IDH1 and PPM1D gene on thyroid nodules is still uncertain and probably benign." (PMID 31085772, 2019).
cancer (143 papers, 2008 to 2025). A tumor composed of atypical neoplastic, often pleomorphic cells that invade other tissues. "Despite the fact that disruption of the PPM1D degradation mechanism strongly promotes cancer progression, the precise mechanism underlying the proteasomal degradation of PPM1D remains incompletely understood." (PMID 40931354, 2025). "Its gene amplification and overexpression are frequently observed in various malignancies and disruption of PPM1D degradation has also been reported as a cause of cancer progression." (PMID 40931354, 2025). "Cancer-associated PPM1D mutations often produce C-terminally truncated proteins that lack degradation signals, resulting in increased stability and activity." (PMID 40931354, 2025). "This work shows how these pathways normally lead to G1 arrest by different routes, and how cancer-associated mutations in WIP1/PPM1D suppress the mitotic-timer pathway in the presence of DNA damage." (PMID 40551011, 2025). "PPM1D is an oncogene in Tier 1 of the COSMIC (Catalogue of Somatic Mutations in Cancer) cancer gene census." (PMID 40931354, 2025). "Dysregulation of PPM1D has been associated with the development of diverse cancers, including breast, ovarian, esophagus, brain, and others." (PMID 38896450, 2024). "Next, we aimed to broaden the analysis of the truncating PPM1D mutations towards oncogene-induced replication stress, which is another physiologically relevant context for cancer development." (PMID 39237765, 2024). "This prevalence is consistent with findings from previous publications reporting the prevalence of PPM1D somatic mutations ranging between 2 and 23.5% in cancer patients with a history of chemotherapy exposure." (PMID 38132396, 2023). "Of note, high levels of active PPM1D are commonly present in cancer cells due to amplification of the chromosomal locus 17q23 or due to gain-of-function mutations in the last exon of PPM1D." (PMID 36651296, 2023). "Our research justifies the need for large population studies allowing a precise evaluation of the cancer risk in carriers of truncating PPM1D mutations as well as the development of new PPM1D inhibitors." (PMID 37709843, 2023). "Overactivation of PPM1D, either through duplication or loss of its degradation domain, is present in several human cancers, including breast cancer, ovarian clear cell carcinoma, and brain cancers." (PMID 37143823, 2023). "PPM1D activity is frequently altered in cancer and different mutations have been reported that primarily result in increased phosphatase activity." (PMID 36060052, 2022). "To assess this, we extended our analysis of PPM1D mutations to include other pediatric and adult cancers." (PMID 35105861, 2022). "The findings reveal how an allosteric inhibitor locks the protein into a conformationally inactive state, and explain the distribution of PPM1D activating mutations in cancer." (PMID 35773251, 2022). "Aberrant expression of the PPM1D gene which encodes a phosphatase called WIP1 is frequently observed in cancers of different origins." (PMID 34771656, 2021). "PPM1D is the second most frequently mutated gene, accounting for 20% of t-MN cases and, as mentioned, it has been linked to previous cancer treatment exposure." (PMID 33562056, 2021). "Recent reports associate gain-of-function mutations of PPM1D in immune cells with worse outcomes for several human cancers." (PMID 34131120, 2021). "Amplifications and mutations of PPM1D has been frequently observed in cancer, and linked to the progression of the disease and therapy resistance phenomena." (PMID 34778245, 2021).